MSI1 (musashi RNA binding protein 1)
Diseases named in the same sentence as MSI1 in open-access papers (continued):
Sharing a sentence is not in itself a finding about the gene and the disease.
cancer (continued). "We thus propose that down-regulation of MYCN in Daoy cancer cells after Msi1 depletion might induce expression of the Wnt repressor DKK1, therefore interconnecting Msi1, Wnt and Hedgehog signaling pathways." (PMID 18826648, 2008). "Thus, we imply that MSI1 is responsible for modulating AKT phosphorylation through multiple indirect ways, including posttranscriptional down-regulation of Numb/PTEN and TNS2, and eventually achieve the survival of cancer cells under chemotherapy." (PMID 27285760, 2016). "Altogether, our results do not support MSI-1 as a robust cancer stem cell marker." (PMID 23374535, 2013). "Furthermore, the contribution of MSI1 to cancer-cell progression and its usefulness as a potential target for cancer therapy have not been examined in animal models in vivo." (PMID 22428049, 2012). "To determine whether physciosporin affects the expression of cancer stemness markers in CRC cells, we monitored the protein expression level of aldehyde dehydrogenase-1 (ALDH1), cluster of differentiation 133 (CD133), CD44, Lgr5, and Musashi-1 (Msi-1) in CSC221 cells." (PMID 31795147, 2019). "Mild yet not significant up–regulation of MSI1 mRNA is also seen in bulk RNA–Seq data of prostate (PRAD), esophageal (ESCA), liver (LIHC) and bladder (BLCA) cancer." (PMID 34062997, 2021).
tumor (99 papers, 2006 to 2025). "High MSI-1 expression was associated with poor survival and advanced tumor stage, grade and vascular invasion." (PMID 37620963, 2023). "Of note, the observation from the treatments of cisplatin/Pep#11/Pep#26 showing significantly greater tumor suppressive effects than cisplatin alone implicated a potential of conquering chemoresistance when MSI1/AGO2 interaction was disrupted." (PMID 35158774, 2022). "MP tumors are generated from neonatal Msi1flox/flox mouse NSCs, and tumor cells are infected with retroviruses encoding GFP (control) or Cre recombinase (for Msi1 excision)." (PMID 36473869, 2022). "Although deletion mutagenesis implicated the potential of the C-terminal fragment of MSI1 (aa 200–362) in tumor suppression, the underlying mechanism remains obscure." (PMID 35158774, 2022). "As an RNA–binding protein, MSI1 is a potent stemness factor with roles in tumor biology implicated by expression and function." (PMID 34062997, 2021). "To address the underlying molecular mechanisms by which MSI1 shuttling promotes stress-induced tumor progression, we characterized MSI1 interacting proteins by mass spectrometry analysis." (PMID 31903115, 2020). "Musashi-1 (Msi-1) is a translational regulator associated with both stem cell and tumour biology that has been recently correlated with OSCC and stage of carcinogenesis." (PMID 23533441, 2013). "In comparison, MSI1 has been characterized as a neural stem cell marker, contributes to the maintenance of self-renewal and differentiation of cells, and has been implicated in the tumorigenesis of multiple tumor types including MB." (PMID 36357906, 2022). "MSI1 causes tumor migration by binding with ICAM1 RNA, leading to poor prognosis." (PMID 35887658, 2022). "Enhancement of MSI1 expression causes tumor spread and relapse." (PMID 32448364, 2020). "We observed that around 5% of non-recurrent pancreatic samples exhibited MSI1 in the cytosol (1/18 cases; data not shown) while 60% of recurrent PDAC samples (37/61 cases) displayed cytosolic MSI1, suggesting that cytosolic MSI1 was associated with tumor recurrence." (PMID 31903115, 2020). "Msi1 and Msi2 are shown to be associated with tumor initiation, progression, and drug resistance." (PMID 28753936, 2017). "Furthermore, an increase in Msi-1 expression has been associated with various tumours of both epithelial and neural origin, some of which are thought to have a stem cell origin." (PMID 23209605, 2012). "Interestingly, some groups have reported that high Msi1 expression potentiates Notch signalling or causes cell-cycle progression in certain tumour cells." (PMID 21486496, 2011). "Similarly, Msi1 is known to be associated with various kinds of tumours, including glioblastoma, hepatoma, and intestinal tumours." (PMID 21486496, 2011). "As hypothesized, the therapeutic window was narrow, with few concentrations adequately targeting G3 MB whilst sparing NSC function suggesting a significant risk of on-target, off-tumor effects predicted from our in vitro results after inhibition of MSI1 in NSCs." (PMID 36473869, 2022). "In some young GC patients, the expression level of MSI1 is thought to be significantly correlated with the depth of tumour infiltration, lymph node metastasis and tumour stage." (PMID 39718205, 2025). "Despite lacking protein-coding potential, RBPmap analysis identified binding sites for key RNA-binding proteins (RBPs) implicated in GBM, including IGF2BP, ELAVL4, and MSI1, which regulate processes such as RNA splicing, stability, and tumor cell self-renewal." (PMID 40076844, 2025). "In a subsequent publication the group found xenograft tumor growth (in nude mice) substantially diminished after MSI-1 knockdown." (PMID 37620963, 2023). "Experimental overexpression of MSI-1 enhanced tumor formation and cell proliferation in vitro and in vivo." (PMID 37620963, 2023). "As MSI1 acts as an oncogene, predicted genes with tumor suppressor function were prioritized in our study." (PMID 37607966, 2023).
tumor (continued). "An overexpression of MSI1 has been reported in different tumor types, including CRCs,36 and MSI1 has been described as a CSC marker in CRC." (PMID 36718360, 2023). "Msi-1 promoter methylation analyses in TCGA dataset revealed reduced levels in primary tumor samples compared to normal endometrium tissue (p < 0.001), supporting increased Msi-1 protein expression in tumor samples." (PMID 35619161, 2022). "Analysis of the xenograft tumor samples indicated the effectiveness of Pep#11/Pep#26 peptides on tumor growth, MSI1/AGO2 interaction, and the downstream mRNA targets." (PMID 35158774, 2022). "Msi1 deletion impair the ability of tumor cells to proliferate and form primary and secondary neurospheres." (PMID 36473869, 2022). "We previously reported that MSI1 mediates stress-induced conditions, such as hypoxia and chemotherapeutic treatments, tumor progression, and recurrence of GBM by translocation to the cytosol and interaction with AGO2." (PMID 35158774, 2022). "Median Msi-1 expression for normal endometrium samples was 6.472 transcripts per million (tpm) compared to 16.813 tpm in primary tumor samples (p < 0.001)." (PMID 35619161, 2022). "In five mice, only small tumor masses were detected, four in Msi-1 knockdown and one in control group." (PMID 35619161, 2022). "Immunohistochemical staining after tumor explantation revealed more apoptotic cells in Msi-1 knockdown tumors, while the mitotic count was significantly decreased (p = 0.071 for dead cells, p = 0.026 for mitosis, n = 14)." (PMID 35619161, 2022). "Building on observations of Msi1 deletion in a syngeneic mouse Myc-amplified G3 MB model, we further determine if similar tumor suppressive effects would be achievable in human models of MYC-amplified G3 MB." (PMID 36473869, 2022). "Mean tumor volume on day 7 was 25.69 mm3 for Msi-1-depleted tumors and 32.22 mm3 for the control group." (PMID 35619161, 2022). "Previous studies had shown that RNA binding protein MSI1 was highly expressed in a variety of tumour tissues." (PMID 35980273, 2022). "The striking tumor suppressive effect of MSI1 inhibition in our syngeneic and PDX models of MB provides evidence for the necessity of MSI1 in G3 MB stem cell self-renewal and propagation." (PMID 36473869, 2022). "In vitro, miR-137 over-expression reduces MSI1 expression, cell and tumor sphere growth, and colony formation while restoring miR-137 expression in xenograft tumor models minimizes tumor growth in vivo." (PMID 33562604, 2021). "Ultimately, Msi1’s impact on this network has important consequences to tumor initiation, growth, and response to therapy." (PMID 33804958, 2021). "Studies on different tumor types have established that a decrease in Msi1 expression affects spheroid growth, cell proliferation, survival, apoptosis and tumor growth." (PMID 35011618, 2021). "Our in vitro studies demonstrated that MSI1 overexpression reversed miR-671-5p-mediated tumor growth, DNA repair, and tumorsphere growth." (PMID 35052701, 2021). "By down-regulating pro-apoptotic genes, overexpression of MSI1 in glioblastoma can protect tumor cells from apoptosis induced by drugs." (PMID 33588867, 2021). "Studies have shown that Musashi-1 (MSI1) is a neural stem cell marker that can maintain tumor stem cell status and cell differentiation." (PMID 35154340, 2021). "Another important tumor suppressor gene showing increased expression after Msi1 silencing is NDRG2, an n-MYC target gene, which is highly expressed in normal tissues, but undetectable in many tumors." (PMID 35011618, 2021). "Restoration of MSI1 expression in xenograft tumor models coincidentally increased tumor growth in vivo." (PMID 35052701, 2021). "Ultimately, Msi1 impact on this network has important consequences in tumor initiation, growth and response to therapy." (PMID 33804958, 2021). "MSI1 is involved in tumor proliferation and maintenance, and it regulates target mRNAs at the translational level." (PMID 32784494, 2020).
tumor (continued). "Collectively, our findings demonstrated that disrupting MSI1/AGO2 interaction with MSI1-C-term decoy suppressed tumor growth by blocking the recruitment of AGO2 to its target mRNAs and subsequently altering their stability." (PMID 31903115, 2020). "Our previous studies reported the correlation between MSI1 expression and GBM migration, drug resistance, tumor progression; but little is known about the underlying mechanism 24-26." (PMID 31903115, 2020). "AGO2 is essential for MSI1 pro-tumor progression as its knockdown 31 inhibited the MSI1-enhanced tumor growth." (PMID 31903115, 2020). "Compared with our previous experiments, cisplatin treatment enhanced tumor growth of xenografts overexpressing MSI1-wt (774.365 mm3vs 477.437 mm3 tumor volume at day 22)." (PMID 31903115, 2020). "Further, we overexpressed or depleted MSI1 in 05MG cell lines to determine the proliferation, anti-apoptosis and tumor progression ability." (PMID 31903115, 2020). "Consistent with findings in other cell models, MSI1 deletion significantly impaired the proliferation and vitality of both adherently growing cells as well as in 3D tumor spheroid models." (PMID 33291443, 2020). "Here, overexpression of MSI1 increased the colony number, anti-apoptosis percentage and tumor volume then Flag-control, whereas depletion of MSI1 showed opposite results." (PMID 31903115, 2020). "Overexpressed C-terminus in tumor cells disrupts endogenous MSI1/AGO2 interaction and reduces tumor volume." (PMID 31903115, 2020). "KEGG pathway analyses revealed an enrichment of candidate target transcripts in adhesion and ECM interaction/regulation pathways, supporting a role of MSI1 in tumor cell adhesion, migration and invasion." (PMID 33291443, 2020). "Although how AGO2 coordinates its functions in response to stresses is still unclear, our findings highlighted a sophisticated mechanism by which MSI1/AGO2 complex promote tumor progression." (PMID 31903115, 2020). "The expression of the stem cell marker CD133 and MSI1 was markedly decreased in miR-153-lentivirus-treated tumor xenografts when compared with control xenografts." (PMID 32375892, 2020). "There is an inverse correlation between miR-137 and MSI1 expression; thus, the overexpression of miR-137 decreases MSl1 expression reducing cell growth, colony formation, and tumor sphere growth." (PMID 31440515, 2019). "Several studies have shown the potential therapeutic target of MSI1 given that when MSI1 is knockdown tumor growth is delayed as well as cell proliferation, migration, and invasion." (PMID 31440515, 2019). "Levels of MSI1/EGFR mRNA expression in tumor tissues from 48 ESCC patients were compared to their corresponding normal tissues using real-time polymerase chain reaction." (PMID 30202417, 2018). "Previous studies have pointed to a tumorigenic role for MSI1, with overexpression of MSI1 leading to tumorigenesis in a mouse xenograft model, and decreased MSI1 leading to reduced tumor progression." (PMID 30097032, 2018). "Knocking down MSI1 using siRNA, miRNA and a small molecule inhibitor led to decreased xenograft tumor growth." (PMID 30097032, 2018). "Levels of EGFR and MSI1 mRNA expression were higher in tumor stage I/II in comparison with stage III/IV, whereas the levels of MSI1 expression were higher than the EGFR expression in patients with tumor stage I/II (1.66 ± 0.45 vs. 1.41 ± 0.52, fold changes)." (PMID 30202417, 2018). "Previously, we have shown that the natural product (−)-gossypol as the first known small molecule inhibitor of MSI1 that down-regulates Notch/Wnt signaling and inhibits tumor xenograft growth in vivo." (PMID 30097032, 2018). "There was a significant correlation between EGFR/MSI1 mRNA expression and grade of tumor differentiation in which 5/7 (71.43%) tumors with concomitant overexpression of these markers were moderately differentiated (p = 0.02)." (PMID 30202417, 2018).
tumor (continued). "The data suggests that the tumor inhibitory effects of LOCCS knockdown are also mediated by MSI1 in TPSC." (PMID 29110645, 2017). "In vivo xenograft model confirmed that the ratio of MSI1/TNS3 expression is important for GBM tumor migration." (PMID 28821879, 2017). "MSI1 expression has been reported in a variety of tumor cells, including colorectal, esophagus, bladder, lung, breast, cervical, and endometrial cancers, medulloblastoma, retinoblastoma, and glioblastoma." (PMID 29064439, 2017). "Current evidences suggest that MSI1 regulates stem cell functions in both normal and malignant colorectal cells, by transcriptionally suppressing genes with the tumor suppressor functions, such as Lrig1, Bmpr1a, Cdkn1a, Pten, p21, Numb and APC." (PMID 29064439, 2017). "Our data also suggested that overexpressed MSI1 induced IL-6 secretion and promoted tumor growth, nevertheless, ablation of IL-6 by the neutralizing antibody withdrawn the malignant phenotypes." (PMID 27285760, 2016). "MSI1 regulates both cellular signaling and tumor-microenvironmental cytokine secretion to create an intra- and intercellular niche for GBM to survive from chemo-drug attack." (PMID 27285760, 2016). "Here, we address that MSI1 protect tumor cells from drug-induced apoptosis and promote tumor growth." (PMID 27285760, 2016). "Although several functional aspects of MSI1 have been characterized, there are still many issues in the molecular mechanism, especially the role in tumor resistance and tumor pathogenicity, remain questioned." (PMID 27285760, 2016). "In conclusion, our data suggest that miR-137 acts as a tumor suppressive miRNA and when down-regulated promotes tumorigenesis through the up regulation of MSI1." (PMID 25940441, 2015). "Univariate analysis showed that FIGO stage, tumor size, and Msi1 expression were significantly correlated with both OS and RFS." (PMID 26499463, 2015). "Ki67 staining was found to express much stronger in the tumor tissues formed by the Msi1-overexpressing HeLa and SiHa cells than in the tumors formed by the control cells." (PMID 25362645, 2014). "The HeLa-Msi1 cells xenographed a tumor much faster (a palpable tumor took 12 days for HaLa-Msi1 cells and 18 days for HeLa-EGFP cells), and the tumor was larger (P<0.05) and heavier (P<0.05) than with the HeLa-EGFP control cells." (PMID 25362645, 2014). "The exogenous Msi1 overexpression in HeLa and SiHa cells enhanced tumor formation in vivo and cell proliferation in vitro as well as in vivo." (PMID 25362645, 2014). "Usingthis classification, we found that Msi2 was highly expressed inLuminal tumors.Msi1 was more variable across tumor subtypes, often showing abimodal profile, split between up- and down-regulation." (PMID 25380226, 2014). "Taken together, these results suggest that the downregulation of MSI1 in the tumors led to a reduction in tumor tissue mass and to disordered cell proliferation and cell-cycle regulation." (PMID 22428049, 2012). "Xenografts of MCF-7 and T47D Msi1 KD cells resulted in a marked reduction of tumor growth, reduced Msi1 and Notch1 expression and increased p21CIP1 expression." (PMID 20727204, 2010). "Comparison of 19 lymph node metastases with their matched primary tumor revealed that Msi1 was highly expressing in 84% of metastases vs. 42% of matched primary tumors." (PMID 20727204, 2010). "We also found that Msi1 increased NOTCH2 levels thus suggesting a potential role of Msi1 in contributing to tumor growth." (PMID 18826648, 2008). "Notably, the MSI/ICAM1 pathway is highly expressed in GBM cells, playing an important role in oncogenic resistance, particularly in enhancing tumor invasion, suggesting that MSI1/ICAM1 represents a promising therapeutic target for GBM." (PMID 40838069, 2025). "Finally, Cre-infected Msi1flox/flox MP cells are intracranially engrafted to determine effects of Msi1 deletion on tumor growth." (PMID 36473869, 2022). "We confirmed Msi-1 knockdown using RT-qPCR analyses on tumor tissues." (PMID 35619161, 2022).